CYP1A2 (cytochrome P450 family 1 subfamily A member 2)
Diseases named in the same sentence as CYP1A2 in open-access papers (continued):
Sharing a sentence is not in itself a finding about the gene and the disease.
tumor (44 papers, 2013 to 2026). "It was observed that the high-expression group of AURKA exhibited higher tumor purity, whereas the high-expression groups of CYP1A2 and ESR1 were associated with lower tumor purity." (PMID 40864066, 2025). "However, high expression of CYP1A1 and CYP1A2 was associated with histological grade, tumor stage, and progression." (PMID 32907554, 2020). "This pronounced difference underscores the potential role of CYP1A2 in tumor biology and suggests its importance as a candidate biomarker or therapeutic target." (PMID 40864066, 2025). "Among the analyzed genes, CYP1A2 exhibited the most significant differential expression, with its expression levels being notably lower in the tumor group compared to the normal group." (PMID 40864066, 2025). "It has been reported that HCC tissues show decreased Cyp1a2 expression when compared to non-tumor tissues." (PMID 38677511, 2024). "The overexpression of this piRNA inhibited Ribonucleotide reductase subunit M2 (RRM2) and Cytochrome P450 1A2 (CYP1A2), two crucial factors for tumor growth and drug resistance." (PMID 34799689, 2021). "Previously, our team demonstrated that down-regulation of CYP1A2 impaired the 17β-estradiol (E2) metabolism, weakening E2-mediated tumor suppression, which contributed to HCC progression." (PMID 33500715, 2021). "Compared to the predominant expression in the non-tumor tissues, the CYP1A2 mRNA level was markedly decreased (by 11.3-fold on average) in HCC samples." (PMID 33500715, 2021). "Among the 7 conditions, the expression levels of cyp1a2 and cyp2c19 in the non-tumor tissues were greater than those in the HCC tissues." (PMID 33757544, 2021). "Our data demonstrated that the reduction of CYP1A2 promoted the growth of HCC whereas its upregulation arrest the tumor progression." (PMID 33500715, 2021). "The significant reduction of CYP1A2 prompted us to examine its potential tumor inhibitory role in HCC." (PMID 33500715, 2021). "For example, as a tumor inhibitor, CYP1A2 suppressed tumorigenicity by inhibiting HGF/MET and reduced the sensitivity of sorafenib via inhibiting the NF-kB signaling." (PMID 34900444, 2021). "Taken together, we showed that the three-gene set (cyp1a2-cyp2c19-il6) was optimized to distinguish HCC from non-tumor samples using random forests with an AUC of 0.973." (PMID 33757544, 2021). "In this study, we have comprehensively provided experimental based evidence to support CYP1A2 as a pivotal tumor suppressor and demonstrated a novel antagonist of HGF/MET signaling in HCC." (PMID 33500715, 2021). "Here, using GEO datasets, we showed that the expression of CYP1A1, CYP1A2, and CYP1B1 was associated with grade, stage, and tumor progression in BC patients." (PMID 32907554, 2020). "The CYP1A2 AA genotype was found to strip the protective effect of caffeine against BC from patients, while patients with the CYP1A2*1F AA genotype experienced slower ER-positive tumor growth upon coffee consumption." (PMID 31477036, 2019). "The CYP1A1 and CYP1A2 mRNA exhibited weak or undetectable expression in both normal (mean Ct>35) and tumor (mean Ct 35.9 and 34.4, respectively) tissues." (PMID 24699256, 2014). "In the present study, we focused on CYP1A2 and genetic susceptibility to CRC which significantly decreased tumor heterogeneity." (PMID 23951174, 2013). "Functional experiments using FTH1‐knockdown/−overexpressing HCC cell lines and xenograft models demonstrated that FTH1 enhances proliferation, migration, and tumour growth by upregulating CYP1A1/CYP1A2 in the tryptophan pathway, thereby increasing the synthesis of 6‐hydroxymelatonin (6‐HMT)." (PMID 40504108, 2026). "However, with LNP-CTNNB1 treatment, tumor cells begin to express Cyp2f2, Arg1, and Ass1 along with diminished expression of Cyp2e1, Cyp1a2, Oat and others." (PMID 40442146, 2025).
tumor (continued). "However, with LNP-CTNNB1 treatment, tumor cells begin to express zone 1 markers, including Cyp2f2, Arg1, and Ass1, while decreasing expression of zone 3 genes (e.g., Cyp2e1, Cyp1a2, and Oat)." (PMID 39711542, 2024). "However, the tumor-promoting effects of OE-circ_0008345 or miR-182-5p inhibitor were both aborted by silencing of CYP1A2." (PMID 38877514, 2024). "Although DMU212 demonstrated selectivity for tumour cells in our in vitro assays, clinical application of this prodrug may be hampered since the compound is also a substrate for CYP1A2 which is predominantly expressed in the liver." (PMID 38257336, 2024). "CYP1A2 was identified as an antagonist of the hepatocyte growth factor/c-mesenchymal–epithelial transition factor (HGF/MET) signaling pathway, which is associated with tumor progression, survival, and metastasis." (PMID 38067357, 2023). "However, there were no significant changes in the expression levels of AHR signaling pathway-related molecules, including AhR, AhRR, Cyp1a1, Cyp1a2, Cyp1b1 and Cox2, in tumor-infiltrating neutrophils from Arnt−/− mice." (PMID 36859266, 2023). "Results showed that CYP1A2 overexpression notably shrank the xenograft tumor volume." (PMID 33500715, 2021). "Taken the previous outcome and our results together, CYP1A2 may serve as a tumor suppressor as well as a novel independent prognostic marker for patients with HCC." (PMID 33500715, 2021). "It is therefore concluded that CYP1A2 can overcome MMPs-mediated tumor progression." (PMID 33500715, 2021). "The transformation of chemicals is important in carcinogenesis the Cyp450 families are key enzymes in tumor transformation, and mediate the metabolic activation of numerous pre-carcinogens, such as Cyp1a2 and Cyp2e1, which degrade xenobiotics, steroids and fatty acids." (PMID 32363190, 2020). "Collectively, CYP1A2 metabolizes E2 to generate the potent anti-tumor agent 2-ME in HCC." (PMID 27093553, 2016). "Several of the genes differentially regulated are associated with tumor initiation (e.g., AhR, CYP1A1, CYP1A2, MDM2, EGR1, NFKBIZ), further suggesting that genomic outcomes of short-term exposure truly reflect the longer-term process of malignant transformation." (PMID 25058030, 2014). "Volcano plots were utilized to visualize the expression patterns of these genes, revealing that genes such as GPC3 and SPINK1 were significantly upregulated in the tumor group, while genes including HAMP and CYP1A2 were markedly downregulated." (PMID 40864066, 2025). "Linoleic acid metabolism is mediated by cytochrome P450 (CYP1A2, CYP2C, CYP2J, CYP2E1, and CYP3A4) to proinflammatory and proangiogenic oxylipins resulting in tumor growth or metastasis." (PMID 35155234, 2022). "In HCC, the suppression of CYP1A2 stimulates HIF-1α upregulation and HGF synthesis to activate MET/PI3K/AKT/NF-κB signaling as well as MMPs, facilitating tumor growth, migration, and invasion." (PMID 33500715, 2021). "To identify the dysregulated CYP1A2 expression, we evaluated both mRNA and protein expression status in HCC tissues and the paired non-tumor tissues." (PMID 33500715, 2021). "The reduction of the tumor volume by CYP1A2 was supported by the deactivated MET and decreased expression of MMPs in xenograft tumor tissues." (PMID 33500715, 2021). "A cut-off point for relative expression of AHR and cytochrome 450 enzymes (CYP1A1, CYP1A2, and CYP1B1; markers of AHR activation) was determined to compare with the grade, stage, and tumor progression." (PMID 32907554, 2020). "Seven CYP450 genes including CYP1A2, CYP2A6, CYP2C8, CYP2C9, CYP2E1, CYP3A4, and CYP4A11 were downregulated in tumor tissues, which were validated in both GSE14520 and GSE36376." (PMID 30148168, 2018). "In our study, we found that several CYPs including CYP1A2, CYP2A6, CYP2C8, CYP2C9, CYP2E1, CYP3A4, and CYP4A11 were all downregulated in tumor tissues in HCC patients." (PMID 30148168, 2018).
tumor (continued). "However, when the carcinogenic PAH and HAA (procarcinogen) are oxygenized by CYP1A1 and CYP1A2 to produce arene oxide, diolepoxide, and other electrophilic reactive species (ultimate carcinogen) that form DNA and protein adducts, they can result in tumor formation and toxicity." (PMID 27999293, 2016). "The rest of the CYPs studied (CYP1A1, CYP1A2 and CYP1B1) showed similar mRNA relative expression levels between tumor and corresponding normal tissues." (PMID 24699256, 2014). "In the present study, we compared the pattern expression of CYP1A1, CYP1A2, CYP1B1, CYP2E1, CYP2W1, CYP3A4 and CYP3A5 in paired tumor and normal tissue of child patients with RMS." (PMID 24699256, 2014). "Using real time quantitative RT-PCR, the gene expression pattern of CYP1A1, CYP1A2, CYP1B1, CYP2E1, CYP2W1, CYP3A4, and CYP3A5 were analyzed in tumor and adjacent non-tumor tissues from 13 child RMS patients." (PMID 24699256, 2014). "PTE is rapidly metabolized by hepatic cytochrome P450 enzymes (CYP1A2, CYP2C9, and CYP3A4) 48, and the tumor microenvironment may further hinder its penetration and activity." (PMID 40520023, 2025). "This study also revealed a notable sequential reduction in serum levels of tumour markers, including carcinoembryonic antigen (CEA) and mouse Cytochrome P450 1A2 (CYP1A2), correlating with a significant decrease in tumour bulk volume upon treatment commencement." (PMID 39058699, 2024). "Concentrations of Gamitrinib that trigger tumor cell killing (IC50 ~1-4 μM) do not affect cytochrome P450 isoforms CYP1A2, CYP2A6, CYP2B6, CYP2C8 or ion channel conductance (Nav1.5, Kv4.3/KChIP2, Cav1.2, Kv1.5, KCNQ1/mink, HCN4, Kir2)." (PMID 35129069, 2022). "Kaplan-Meier analysis revealed that the elevated CYP1A2 expression was statistically correlated with longer tumor-free survival (TFS) but not overall survival (OS)." (PMID 33500715, 2021). "In addition, IHC staining showed a significant weak expression of CYP1A2, with 2.6-fold suppression, in HCC tissues compared with adjacent non-tumor tissues." (PMID 33500715, 2021). "Both CYP1A2 and CYP3A4 were predominantly observed staining in the cytoplasm of tumor cells." (PMID 28418906, 2017). "Thus, the aim of the present study was to determine the mRNA expression pattern of seven representative CYPs (e.g., CYP1A1, CYP1A2, CYP1B1, CYP2E1, CYP2W1, CYP3A4, and CYP3A5) in paired tumor and normal tissue of childhood patients with RMS." (PMID 24699256, 2014).
infection (17 papers, 2014 to 2025). The state of being infected such as from the introduction of a foreign agent such as serum, vaccine, antigenic substance or organism. "Because CYP1A2 accounts for the majority of clearance, any change in smoking status, infection (cytokine-mediated CYP1A2 suppression), or co-prescribed inhibitors/inducers warrants repeat therapeutic drug monitoring." (PMID 40566484, 2025). "Severe infection and clozapine itself can lead to alterations in interleukin-6, interleukin-1, interferon-ɣ and tumor necrosis factor-α leading to decreases in CYP1A2 and the body’s capacity to metabolize clozapine." (PMID 40704031, 2025). "On the other hand, Cyp1a2, Cyp3a25, Ugt1a6 and Ugt1a9, although down-regulated at 8 days post-infection, showed minimal effects at 6 and 12 days post-infection." (PMID 31299982, 2019). "The patient metabolized the CYP1A2 drugs clozapine and olanzapine normally but got intoxicated on clozapine during an infection." (PMID 26000191, 2015). "Similar to H19 overexpression though, silencing H19 expression also up‐regulated most of the genes involved in lipid breakdown, such as Acat2, Cpt1b, Ndafs4, Pck2, Cyp1a2, Acads and Atpsa1, at 72 hours after Ad‐H19 infection, although most of them were down‐regulated at 36 hours after infection." (PMID 31809000, 2020). "Cytokines released in systemic inflammation with or without infection increase blood clozapine concentration by inhibiting the metabolism of CYP1A2." (PMID 38355481, 2024). "The rs951840747 (CT) (p = 0.01) of CYP1A2 was significantly associated with PZQ efficacy and had the highest OR, implying that individuals possessing this genotype had a 3.61 (95% CI: 1.30, 10) increase in odds of clearing infection compared to those without this genotype." (PMID 35754834, 2022).
kidney disease (5 papers, 2018 to 2024). "It has been reported the CYP1A2 genotype may modify the association between coffee intake and kidney disease; caffeinated coffee intake has been shown to be associated with an increase in the risk of kidney disease in slow metabolizers but not fast metabolizers." (PMID 38963648, 2024).
psychiatric disorder (4 papers, 2014 to 2023). A disorder characterized by behavioral and/or psychological abnormalities, often accompanied by physical symptoms. "In the patients with psychiatric disorders of the present study, significant association was observed between CYP1A2 expression in leukocytes and olanzapine metabolizing activity." (PMID 37898643, 2023). "The main aim of the present study was to evaluate the influence of CYP1A2 polymorphisms on CYP1A2 activity and mRNA expression in human liver samples and in patients with psychiatric disorders." (PMID 35335907, 2022). "The CYP1A2 alleles, including CYP1A2*1C, CYP1A2*1D, CYP1A2*1F, CYP1A2*1L, CYP1A2*1M, CYP1A2*1V and CYP1A2*1W, were reconstructed from −3860G>A, −2467delT, –739T>G, −163C>A or 2159G>A SNP data in liver tissue donors and in patients with psychiatric disorders." (PMID 35335907, 2022). "In the patients with psychiatric disorders, only six were on carbamazepine therapy, three displayed intermediate CYP1A2 expression and three were CYP1A2 poor metabolizers." (PMID 35335907, 2022). "The relative frequencies of the CYP1A2 haplotypes and genotypes in the liver tissue donors and patients with psychiatric disorders were compared to those reported in Caucasian populations." (PMID 35335907, 2022). "The present study focused on the impact of CYP1A2 and CYP2D6 genetic polymorphisms as well as CYP1A2 metabolizing capacity influenced by non-genetic factors (sex, age, smoking behaviour) on olanzapine blood concentration in patients with psychiatric disorders." (PMID 37898643, 2023). "The CYP1A2 genotype of the patients with psychiatric disorders was determined from CYP1A2 SNP data (including −3860G>A, −2467delT, −739T>G, −163C>A and 2159G>A) by haplotype analysis, whereas the hepatic CYP1A2 function was estimated from CYP1A2 mRNA expression in patients’ leukocytes." (PMID 35335907, 2022). "The CYP1A2 SNPs most common in Caucasian populations (−3860G>A, −2467delT, −739T>G, −163C>A and 2159G>A) were identified in 151 liver tissue donors and in 274 patients with psychiatric disorders." (PMID 35335907, 2022). "The present work focused on the impact of CYP1A2 and CYP2D6 genetic polymorphisms as well as of CYP1A2 metabolizing capacity influenced by non-genetic factors (sex, age, smoking) on olanzapine blood concentration in patients with psychiatric disorders (N = 139)." (PMID 37898643, 2023). "In addition to the CYP1A2 and CYP2D6 variations, a multiple linear regression analysis was performed to estimate the influence of non-genetic factors, sex and age as well as of tobacco smoking, the CYP1A2 inducing factor on olanzapine exposure in patients with psychiatric disorders." (PMID 37898643, 2023). "The CYP1A2*1C, CYP1A2*1D and CYP1A2*1E alleles were identified in 0.4–4%, 3.4–11% and 0.4–6% of the Caucasian populations; however, these alleles were detected neither in the tissue donors nor in the patients with psychiatric disorders." (PMID 35335907, 2022). "The association of olanzapine plasma concentration normalized by the dose/bodyweight (C/D) with CYP1A2 and CYP2D6-status was investigated in patients with psychiatric disorders." (PMID 37898643, 2023). "The present study involving patients with psychiatric disorders investigated the role of CYP1A2 and CYP2D6 genetic variants and patients’ CYP1A2 metabolic capacity influenced by non-genetic factors (e.g., sex, age, smoking behaviour) in olanzapine exposure." (PMID 37898643, 2023). "Second, CYP1A2*1F was not identified in the liver tissue donors and was detected at extremely low frequency (0.4%) in the patients with psychiatric disorders; therefore, the effect of CYP1A2*1F on CYP1A2 activity or expression was not assessed." (PMID 35335907, 2022). "CYP1A2 and CYP2D6 are important for the metabolism of psychoactive drugs, including SSRIs, and an increased hypersensitivity to these medications was described in ASD subjects compared to patients with other psychiatric disorders." (PMID 35663546, 2022).
psychiatric disorder (continued). "However, smoking habits and CYP1A2-inducer therapy (with carbamazepine) were well documented in the group of patients with psychiatric disorders; therefore, the impact of these non-genetic phenoconverting factors on the CYP1A2 expression was reliably investigated." (PMID 35335907, 2022). "Although the impact of smoking on CYP1A2 expression was reliably evaluated in the patients with psychiatric disorders, oral contraceptives were not applied in these patients; therefore, no conclusion on the CYP1A2 activity-reducing effect of these drugs could be drawn." (PMID 35335907, 2022).
cardiovascular disease (3 papers, 2020 to 2024). "(±)Warfarin, an anticoagulant for cardiovascular disease but with narrow therapeutic window, were substrates of CYP1A2/3A4(R-form), 2C9(S-form) and BCRP." (PMID 32985569, 2020).
metabolic disorders (3 papers, 2017 to 2024). "In this case, the patient experienced tizanidine-induced bradycardia at a low dose of tizanidine (2 mg) without drug interactions, metabolic disorders, or structural cardiac disease, and there was no history of sudden smoking cessation that could cause a rapid decrease in CYP1A2 enzyme activity." (PMID 38894773, 2024).
movement disorder (2 papers, 2012 to 2021). Neurological conditions resulting in abnormal voluntary or involuntary movement, which may impact the speed, fluency, quality and ease of movement. "In a population with chronic mental illness, various SNPs in 10 candidate genes (PPP1R1B, BDNF, DRD3, DRD2, HTR2A, HTR2C, COMT, MnSOD, CYP1A2, and RGS2) reached nominally significant (p≤0.05) associations with drug-induced movement disorder." (PMID 22615781, 2012).
retinopathy (2 papers, 2014 to 2022). "Our results point to the involvement of Cyp1a2 and Cyp1b1 in the pathogenesis of AMD-like retinopathy in OXYS rats." (PMID 25132985, 2014).
CYP1A2 also shares sentences with these, for which no sentence is quoted: bipolar disorder (3 papers); influenza (3); agranulocytosis (2); allergic disease (2); cardiac disease (2); end stage renal disease (2); gastric cancer (2); Huntington disease (2); hyperglycaemia (2); hyperlipidemia (2); immune dysfunction (2); Nephropathies (2); neurodegenerative disease (2); primary sclerosing cholangitis (2); sleep disorder (2); acute liver failure (1); acute myocardial infarction (1); Adrenal insufficiency (1); age-related macular degeneration (1); Allergy (1); androgen excess (1); anxiety disorder (1); Arthritis (1); aspiration pneumonia (1); autoimmune disease (1); autoimmune hepatitis (1); behavioral disorders (1); blepharospasm (1); breast neoplasm (1); cerebral infarction (1).
A further 60 diseases each share a sentence with CYP1A2 in 1 paper.